OLIG2 (oligodendrocyte transcription factor 2)
Diseases named in the same sentence as OLIG2 in open-access papers (continued):
Sharing a sentence is not in itself a finding about the gene and the disease.
tumor (continued). "In mice, TSM phosphorylation of Olig2 is essential for tumor growth and resistance to genotoxic damage." (PMID 32483381, 2020). "Enhanced DLK1 levels in PDGFB + DLK-A tumors were confirmed by co-staining with the tumor marker Olig2." (PMID 32205867, 2020). "Olig2 expression was observed in the majority of tumor cells, and was expressed highly in microcystic areas of the tumor and also in the fibrillated areas." (PMID 31427603, 2019). "Bulk transcriptomic analysis of eGFP+ tumor cells from these mice showed upregulation of specific stem cell markers, including Sox2, Gfap, Olig1, Olig2, Blbp (Fabp7) and Pdgfra31." (PMID 31863004, 2019). "Similar to human MBs,4 we showed that a minor cell population in tumor lesions—including many Sox2+ cells—expressed Olig2 protein." (PMID 31763624, 2019). "OLIG2 expression has been previously linked to migration/invasion, both in normal and in malignant cells, and OLIG2-expressing cells have been found both at the GBM tumor core and peritumoral rim." (PMID 28821904, 2018). "Immunostaining was performed on day 3 postinfection, and ZIKV preferentially infected the Olig2+ bulk tumor cells." (PMID 30228241, 2018). "In the GFAP positive tumour surrounding brain parenchyma of aCP, several Sox2+ cells showed co-expression of Olig2." (PMID 29158570, 2017). "Ki67 staining indicated strong proliferation, and uniform expression of GFAP and Olig2 confirmed the glial nature of all tumours." (PMID 28695888, 2017). "The frequency of OLIG2-positive cells varied in the different tumor cultures as did the expression of SOX2." (PMID 28148893, 2017). "Coherently to our in vitro observations, we found that SSADH staining prevailed in proliferative/non-differentiated GBM territories (PHIGH/D−) containing mitotic and Olig2 + tumor cells." (PMID 28032215, 2017). "To gain more information about the properties of Sox2+ and Sox9+ cells located near the aCP, we decided to perform double-immunofluorescence staining of selected tumour samples using antibodies against Sox2 or Sox9 and Olig2." (PMID 29158570, 2017). "Genetic analysis with microarray data showed an enrichment of proneural markers as OLIG2 in the IE tumours, whereas CE tumours expressed VEGF, MMP7 and Matrix Gla proteins." (PMID 27350391, 2016). "Tumors also co-expressed astrocyte and neural stem cell marker Gfap and Olig2, which is rare in normal brain cells, and indicates aberrant cell fate specification typical of tumor cells." (PMID 27713119, 2016). "In 29 patients with available tumor specimens, tumors with high expression of either LIN28 or OLIG2 or elevated level of Rad51 were significantly associated with poorer prognosis." (PMID 27074032, 2016). "There was strong immunoreactivity for GFAP and OLIG2 in many tumor cells, while all tumor cells expressed S-100 and MAP-2." (PMID 25955030, 2015). "Sox-2, Olig-2 and GFAP were present at high levels in proliferative cells and expressed in the invasive part of the tumor, and T121 staining confirmed suppression of RB (Sox-2, Sox-2/I, Olig-2, Olig-2/I, T121, T121/I and GFAP, GFAP/I)." (PMID 25431423, 2015). "This revealed that Pax3 expression is primarily found within the Olig2-tumor cell compartment of BSG." (PMID 25330836, 2014). "We postulate that as cells exit the tumor mass and infiltrate brain parenchyma, OLIG2 expression is enhanced, and as they colonize brain parenchyma, expression of EMT markers is diminished." (PMID 25365423, 2014). "Some possible transcripts involved in the promotion of quiescence and the differentiation state in Olig2 tumor cells seem to be deleted during tumorigenesis." (PMID 24738058, 2014).
tumor (continued). "The presence of OLIG2 positive tumor cells within the AOI strongly suggests that the invasive niche contains GSCs." (PMID 25365423, 2014). "Immunohistochemically, the tumor cells showed perinuclear positivity for synaptophysin (Syn) and focal positivity for oligodendrocyte transcription factor 2 (Olig2)." (PMID 24179531, 2013). "As in tumor, relative TE values in Olig2-positive OPCs in adult normal brain varied widely amongst mRNA species and were highly correlated across replicates (average R = 0.959)." (PMID 23056544, 2012). "Comparison of relative ribosome occupancies of tumor and normal Olig2-positive cells revealed a positive correlation of 0.616, demonstrating substantial similarity in the measured translation states of the two cell populations." (PMID 23056544, 2012). "To do this, we plotted the gene expression data from whole tumors relative to the gene expression data from the Olig2-expressing tumor cells that had been sorted from the rest of the tumor." (PMID 22393407, 2012). "Strong expression of Olig2 by immunohistochemistry was seen in 13/13 tumors in this group vs 3/8 in group 2 tumours (p value = 0.003, chi square test with McNemar correction)." (PMID 22389665, 2012). "We also show that TAAs are derived from the non-tumor, stromal environment, in contrast to the Olig2+ tumor cells that constitute the neoplastic elements in our model." (PMID 22393407, 2012). "GFP expression also allowed flow cytometric sorting of Olig2+tumor cells to isolate total cellular RNA from the same cell population." (PMID 23056544, 2012). "It is worth noting that a large percentage of PDGF-RFP infected cells expressed low levels of GFP and, given our staining and FACS data, these represent PDGF-infected Olig2+ tumor cells that also express low levels of GFAP." (PMID 22393407, 2012). "In summary, the analysis of cells in the neoplasia-like areas revealed accumulation of highly proliferative abnormal glial precursor cells displaying Gfap-positivity and frequent Olig2 and Pdgfr-α positivity coupled to a high proliferation rate." (PMID 21490965, 2011). "However, Olig2 positivity in the majority of tumor nuclei raised concern for an alternate diagnosis." (PMID 40724977, 2025). "OLIG2 is enriched at tumour margins, supporting stemness and invasion." (PMID 41179304, 2025). "Olig2 showed strong to moderate immunopositivity in the majority of tumor nuclei." (PMID 40724977, 2025). "Notably, OLIG2 protein was enriched in elongated cells in sparse areas of the tumor, identifying it as a marker of cells that individually penetrate the brain parenchyma." (PMID 40683881, 2025). "Interestingly, OLIG2-positive cells in 8DGC-GFP localized at the invasive tip were found to be more abundant than those at the tumor center." (PMID 40184918, 2025). "ASCL1 and OLIG2 dynamically interact, affecting tumour cell types, migration, and proliferation." (PMID 39457550, 2024). "Similar to Ascl1-CKO, Olig2-CKO resulted in 100% tumor formation with a median survival of 92 days." (PMID 39609428, 2024). "In the RGNT samples, compared with the non-tumour regions, strong stainings of OLIG2, SOX10, NG2 and PDGFRA were observed in the neurocytic regions in all samples analysed, and the astrocytic regions of the same samples showed sporadic and weaker expression of OLIG2, SOX10, NG2 and PDGFRA." (PMID 38764775, 2024). "Interestingly, there was a noticeable reduction in tdTOM+ tumor migration along the corpus callosum to the contralateral hemisphere, even at terminal stages, although OLIG2 was still present in these tumors." (PMID 39609428, 2024). "Costaining of the panmacrophage marker F4/80 with C3 and the tumor cell marker Olig2 revealed that C3 expression itself was found in areas staining positive for both F4/80+ and Olig2+ cells, indicating that C3 expression can conceivably come from both these cell types in murine GBM." (PMID 39172519, 2024).
tumor (continued). "Thus, in the absence (Olig2-CKO) or presence of lower levels of OLIG2 (Ascl1-OE) within tumor cells, ASCL1 is able to escape this dimerization or repression to potently activate NSC/astrocyte genes." (PMID 39609428, 2024). "Notably, terminal control tumors exhibited a much higher percentage of SOX10+ cells (~90%) than OLIG2+ cells (61%), whereby SOX10 was observed in a subset of OLIG2-;tdTOM+ tumor cells." (PMID 39609428, 2024). "Based on their developmental roles in glial cell fate specification, we hypothesized that altering the levels of ASCL1 and/or OLIG2 should influence the cell or tumor types of the GBM mouse model." (PMID 39609428, 2024). "Indeed, the migration distance of Ascl1-OE GFP+ tumor cells on the contralateral corpus callosum was similar to that of Olig2-CKO tumors." (PMID 39609428, 2024). "Pathological evaluation of the tumor using histopathological features showed diffuse immunoreactivity for oligodendrocyte transcription factor 2 (OLIG-2), weak to moderate immunoreactivity for neuronal nuclear protein (Neu-N), and focal immunoreactivity for CD56." (PMID 39650896, 2024). "However, despite this similarity, the immunofluorescent levels of ASCL1 in Olig2-CKO tumor cells were slightly lower than control and significantly lower compared to Ascl1-OE tumor cells." (PMID 39609428, 2024). "Finally, sulfopin or RO3306 treatment alone targeted the GSC population in tumor tissues as indicated by the reduced OLIG2+ cells, while combined treatment more efficiently impaired GSCs in vivo." (PMID 38167292, 2024). "Our results revealed regional heterogeneity in the tumor-like structures of GBs, with OLIG2+ stem cell populations occupying hyperoxic, highly nutritious regions at the periphery, while GFAP+ differentiated cells resided in chronic hypoxic necrotic regions at the core." (PMID 38390494, 2024). "Tumors were stained for C3, GFAP as an astrocytic marker, and Olig2 for the bulk of tumor cells." (PMID 39172519, 2024). "Due to the ability of ASCL1 and OLIG2 to directly bind to the other’s loci and loci of cell cycle genes, we next investigated how alteration of the levels of ASCL1 and/or OLIG2 affect each other’s expression and tumor cell proliferation at both early and terminal stages of the various tumor types." (PMID 39609428, 2024). "The fact that ASCL1 and OLIG2 can physically and genetically interact suggests that OLIG2 may directly repress ASCL1’s ability to promote tumor migration through these interactions." (PMID 39609428, 2024). "On the other hand, Olig2–tumor cells migrate via blood arteries as cell clusters." (PMID 38473812, 2024). "In Sonic Hedgehog (SHH)-subgroup MB, OLIG2-expressing tumor stem cells drive recurrence." (PMID 37333134, 2023). "Bioinformatic analyses revealed five major cell types based on hallmark gene expression: myeloid (Cd11b; 12 clusters), lymphoid (Cd33/Ncr1/B220/Cd19; five clusters), tumor (Olig2/Cd276/Col11a1; one cluster), endothelial (Enpp2; one cluster), and fibroblast (plp1/Ptgds; one cluster) cells." (PMID 37971169, 2023). "Log-rank test was performed to access the factors that may interfere with patients’ OS, including age, gender, tumor diameter, resection extent, OLIG2 expression level, and adjuvant therapy in cGBM patients." (PMID 37001387, 2023). "Additionally, several studies utilizing transgenic mouse models showed that ablation of Olig2 delayed tumor growth and improved survival." (PMID 37274223, 2023). "Meanwhile, OLIG2 expression level may be used as an indicator for tumor relapse and the effectiveness of adjuvant therapy." (PMID 37001387, 2023).
tumor (continued). "As OLIG2+ cells make up only a fraction of the proliferative population within MB, we expected that OLIG2 inhibitor therapy would require combination with additional therapies for optimal anti-tumor effect." (PMID 37333134, 2023). "Further immunohistochemical staining did not yield a clear classification of the tumors regarding either neural or astroglial origin: The early tumor cells (P21 mice) were positive for oligodendrocyte lineage marker OLIG2 and SOX2, a marker for CNS progenitor cells, e.g. NSCs." (PMID 37407554, 2023). "To test the potential for simultaneous inhibition of CDK4/6 and OLIG2 to produce a greater anti-tumor effect compared to either intervention alone, we treated replicate G-Smo mice with POx-Palbo plus CT-179 and then compared PK effects and efficacy versus CT-179 alone or POx-Palbo alone." (PMID 37333134, 2023). "Bioinformatic analyses revealed five major cell types based on hallmark gene expression: myeloid (Cd11b; 12 clusters), lymphoid (Cd33/Ncr1/B220/Cd19; 5 clusters), tumor (Olig2/Cd276/Col11a1; 1 cluster), endothelial (Enpp2; 1 cluster) and fibroblast (plp1/Ptgds; 1 cluster) cells." (PMID 37333156, 2023). "Histopathologically, the tumor presented a solid growth pattern and immunonegativity for Olig2." (PMID 36104744, 2022). "Interestingly, in our study TMZ treatment increased the percentage of qProm1-derived cells expressing OLIG2 in the core of the tumor." (PMID 35970913, 2022). "Morphologically, this tumor was composed of two distinct glial histopathological components: one solid with ependymal features (pseudorosettes and true rosettes) and a weak expression of Olig2 and one infiltrative component with an Olig2 expression." (PMID 36104744, 2022). "Immunostaining for GFAP and OLIG2 revealed entrapped reactive glial cells among all tumor samples." (PMID 36423085, 2022). "Reactivity for Olig2 was observed in the astrocyte‐like tumor cells to varying degrees." (PMID 33576087, 2021). "While these effects passed undetected in bulk transcriptomic studies, the fractions of OLIG2+ tumor cells and MHCII-expressing macrophages were effective biomarkers that distinguished radioresistant stem cell-derived tumors from radiosensitive tumors originating in CGNPs." (PMID 34021242, 2021). "However, scRNA-seq analysis demonstrated that G-Smo tumors, generated by initiating SmoM2 expression in Gfap-expressing CNS stem cells, contained more proliferating cells at P15 and more Olig2+ tumor stem cells." (PMID 34021242, 2021). "It is however very useful in the differential diagnosis of a diffuse glioma and a neuronal, ependymal, or nonglial tumor type because OLIG2 staining is characteristically restricted or deficient in the latter." (PMID 34797306, 2021). "Interestingly, cells expressing NES or OLIG2 were present both in the margin and in tumours, while being highly correlated." (PMID 34948016, 2021). "In contrast to the other cases, subpopulations (approximately 20%) of tumor cells expressed Olig2." (PMID 33481105, 2021). "Foci of myxoid degeneration and microvascular proliferation could be found and the tumor cells exhibited extensive Olig2 immunoexpression." (PMID 32650833, 2020). "Higher expression of OLIG2 modules distinguishes infiltrating tumor from cellular tumor samples." (PMID 32383980, 2020). "Olig2, a CNS-specific TF, is well known to support tumor development." (PMID 32483381, 2020). "In our series all OLIG2 positive tumours were PAX3/7-FOXO1 fusion positive." (PMID 31493794, 2019). "Tumor cells expressing Olig2, GFAP, or both by F-IHC were observed in all tumors analyzed." (PMID 31427603, 2019). "Olig2 decreased in the tumor relapses for BT35 and BT69, as in the corresponding cell lines." (PMID 31779235, 2019). "We confirmed that Olig2 and Sox10 are highly expressed in tumor tissue, supporting a mechanism in which oligoneural precursor transcription factors contribute to gene expression driving tumor cell proliferation." (PMID 29914980, 2018).
tumor (continued). "Furthermore, similar invasion of the cerebral cortex and Ki67 and Olig2 staining were observed in both tumor types." (PMID 30416682, 2018). "Similarly, we found large areas in tumor sections coexpressing proneural and mesenchymal subtype markers OLIG2 and YKL-40 (Figure 4Bii, marked area)." (PMID 28744448, 2017). "In addition, we also investigated the co-expression of Sox2 and Sox9 with the oligodendrocyte transcription factor 2 (Olig2) as well as the glial fibrillary acid protein (GFAP) to define tumour surrounding cerebral microenvironment." (PMID 29158570, 2017). "However, GBM18 showed irregular boundaries, with cells migrating out of the main tumor mass, and significantly higher OLIG2 expression than GBM38." (PMID 27589567, 2016). "However, using tumor staining for Olig-2, Nestin and GFAP, we demonstrated that our preclinical model represents a range of GBM cell types, therefore modeling the heterogeneous cell population in human GBM." (PMID 25431423, 2015). "In contrast, ROBO1 disconnects N-cadherin from the cytoskeleton in invasive cells, thus increasing their motility; c-MYB induces expression of MGMT, resulting in higher chemoresistance; expression of SOX2 and OLIG2 result in greater stemness and higher capacity for tumour formation." (PMID 23818228, 2013). "In these tumors, eGFP-L10a expression was restricted to Olig2+cells in the tumor." (PMID 23056544, 2012). "Interestingly, we did not detect differences regarding the total number of invading OLIG2+ tumor cells in the invasive zone but found a significantly higher proportion of vessel co-opting tumor cells in Pdgfbret/ret animals, indicative of a more permissive PVN in the absence of pericytes." (PMID 41339360, 2025). "Furthermore, ASCL1 and OLIG2 function redundantly to promote tumor formation and proliferation." (PMID 39609428, 2024). "This tumour is usually GFAP-positive but may lack OLIG2 and SOX10." (PMID 39126064, 2024). "These methods showed that the disruptive effects of different agents on OLIG2 dimerization correlated with the inhibitory effects of these agents on in vitro tumor cell growth, supporting the proposed mechanism of action of these agents and the specificity of their anti-tumor effect." (PMID 37333134, 2023). "However, OLIG2-expressing cells are also found in other subgroups and that OLIG2 may contribute to tumor heterogeneity across MB disease subsets, which may explain the response observed in the Group-3 Neo-113 model." (PMID 37333134, 2023). "However, OLIG2 function in oligodendrocytes may be fundamentally different from OLIG2 function in tumor cells, where it modulates the chromatin landscape to activate a unique oncogenic program." (PMID 37333134, 2023). "Additionally, we detected the expression of Olig2 and CD133 in tumor tissues using immunohistochemical staining and the results indicated that Olig2 and CD133 protein level was decreased clearly in the ACT001-treated groups versus control group and ADR group (5j)." (PMID 36990974, 2023). "Indeed, we found significantly higher numbers of Olig2+ cells outside the tumor bulk in PDGFB + DLK-A brains compared with controls, indicating that DLK-A may drive invasive tumor growth." (PMID 32205867, 2020). "Importantly, OLIG2 is expressed in virtually all CD133+ tumor-initiating cells and in the vast majority of Ki67+ proliferating cells in GBM, suggesting that it may promote tumor formation." (PMID 25008045, 2014). "We observed a significant increase over time in the interactions between SOX2/OLIG2 high tumor cells and different tumor cell populations, including p-TYR high and translating GFAP- tumor cells." (PMID 41568176, 2026).